ATF3 (activating transcription factor 3)
Diseases named in the same sentence as ATF3 in open-access papers (continued):
Sharing a sentence is not in itself a finding about the gene and the disease.
steatosis (5 papers, 2022 to 2024). Increased lipid within the cytoplasm of cells. "ATF3-dependent RIPK3 induction, causing a modal shift of hepatocellular death, can be a therapeutic target for steatosis-induced liver damage, including NASH." (PMID 36690638, 2023). "We found that the mode of hepatocellular death switches via ATF3-dependent RIPK3 induction from apoptosis to necroptosis with exacerbation of steatosis in obese mice fed a high-fat diet (HFD) after partial fatty liver resection." (PMID 36690638, 2023). "Compared with the control group, Nqo1, Atf3, and Cdkn1a were up-regulated in MCD diet-fed mice, and gradually increased with the aggravation of steatosis and inflammation." (PMID 37305039, 2023). "Compared with wild-type mice, mice lacking or overexpressing hepatic ATF3 exhibit decreased or increased RIPK3 expression in severe hepatic steatosis and necroptosis after partial hepatectomy." (PMID 38826193, 2024). "The frequency of either ATF3+ or RIPK3+ hepatocytes increased in accordance with an increase in the scores of ballooning, but not that of steatosis." (PMID 36690638, 2023).
tongue squamous cell carcinoma (5 papers, 2021 to 2025). A squamous cell carcinoma that arises from the tongue. "Here we discovered that ATF3 plays an anti-tumor role in tongue squamous cell carcinoma (TSCC) cells through the transcriptional suppression of its new downstream targets interferon alpha inducible proteins 6 (IFI6) and 27 (IFI27)." (PMID 33539340, 2021). "In this study, we examined biopsies of tongue squamous cell carcinomas (TSCCs) and found that the nuclear expression level of ATF3 correlated negatively with the differentiation status of TSCCs, which was validated by analysis of the ATGC database." (PMID 33539340, 2021). "Similarly, ZNF671-initiated downregulation of ATF3 is consistent with its role as a negative regulator in the growth and migration of human tongue SCC cells in vitro." (PMID 39595048, 2024). "Activating transcription factor 3 (ATF3) downregulates IFI6 to suppress the growth and migration of tongue squamous cell carcinoma cells." (PMID 35717249, 2022).
amyotrophic lateral sclerosis (4 papers, 2015 to 2024). Amyotrophic lateral sclerosis (ALS) is a neurodegenerative disease characterized by progressive muscular paralysis reflecting degeneration of motor neurons in the primary motor cortex, corticospinal tracts, brainstem and spinal cord. "ATF3 expression has also been reported in amyotrophic lateral sclerosis model mice; motor neurons express ATF3 in the symptomatic stage." (PMID 38238800, 2024). "Atf3 was detected in the skeletal muscle and spinal cord motor neurons in paralyzed mouse with amyotrophic lateral sclerosis." (PMID 35812340, 2022). "ATF3 is induced by stress and is related to cardiac contractility abnormalities and muscular disorders such as amyotrophic lateral sclerosis." (PMID 25567521, 2015). "Furthermore, in a transgenic mouse model of amyotrophic lateral sclerosis, increased Atf3 gene expression in motor neurons extended the survival of injured motor neurons." (PMID 38649772, 2024).
astrocytoma (4 papers, 2016 to 2023). "Neural precursor cell-derived endovanilloids and Arvanil, a TRPV-1 agonist, induces cell death in high-grade astrocytoma via the TRPV-1-mediated activating transcription factor-3 endoplasmic reticulum stress pathway." (PMID 26888607, 2016). "In addition, stimulation of TRPV1 could activate ATF3‐ER stress pathway, and help neural precursor cells to induce the cell death of high‐grade astrocytomas." (PMID 38093622, 2023). "Infection of astrocytoma cells with CHIKV resulted in a slight, but significant, increase in ATF3 transcription." (PMID 35746681, 2022). "Infection with RVFV induced significant upregulation of ATF3, FOS, KLF4, CXCL10, TNF-α, and PTGS2 in astrocytoma cells at 16 hpi." (PMID 35746681, 2022). "Infection of the astrocytoma cells with EEEV resulted in a significant upregulation of transcription factors ATF3, FOS, and JUN, with both ATF3 and JUN being at least partially transcriptionally dependent on EGR1." (PMID 35746681, 2022).
colorectal tumor (4 papers, 2016 to 2023). "It has been reported that the expression of ATF3 is lower in human colorectal tumors than in normal adjacent tissues, while overexpression of ATF3 in vivo can reduce the volume of mouse tumor xenografts by 54%." (PMID 33407456, 2021). "On the other hand, phlorofucofuroeckol A seems to have the capacity to stimulate the expression of activating transcription factor 3 (ATF3), consequently inducing apoptosis in four different colorectal tumor cell lines namely HCT116, SW480, LoVo and HT-29 cells." (PMID 34202184, 2021).
influenza (4 papers, 2011 to 2023). An acute viral infection of the respiratory tract, occurring in isolated cases, in epidemics, or in pandemics; it is caused by serologically different strains of viruses (influenzaviruses) designated A, B, and C, has a 3-day incubation period, and usually lasts for 3 to 10 days. "Atf3-expressing CAP1s proliferate and increase in number after influenza infection, and endothelial-specific loss of Atf3 results in the persistent dysmorphic alveolar structure during the tissue repair process." (PMID 37233732, 2023). "It was also found to negatively regulate TLR signaling pathways in influenza infection, and ATF-3 -/- mice were more susceptible to hypercytokinemia." (PMID 22074594, 2011). "Transcriptional changes due to loss of Atf3 after acute influenza injury." (PMID 37233732, 2023). "This reveals a putative role for Atf3-expressing CAP1_Bs in the regenerative response of the endothelium to influenza infection." (PMID 37233732, 2023). "(G) IF for tdTomato, ERG, and Endomucin-1 in H1N1-infected Atf3-tdTm mice at 22 dpi demonstrates an increase in Atf3-positive ECs in the alveolar space after influenza (inset marked by white box)." (PMID 37233732, 2023). "Here, we show that the transcription factor Atf3 is essential for the regenerative response of the mouse pulmonary endothelium after influenza infection." (PMID 37233732, 2023). "The role of Atf3 in regulating inflammatory response suggests that immune-endothelial signaling may play an important role in vascular regeneration after influenza." (PMID 37233732, 2023). "While knockout of endothelial ATF3 does not affect alveolar inflammation and tissue damage at 21 days post influenza infection, it does cause formation of abnormal alveolar structures characterized by enlarged airspaces and defective alveolar regeneration." (PMID 37515150, 2023). "Our data suggest that Atf3 may be one factor that maintains this balance in the lung after an influenza infection." (PMID 37233732, 2023). "Notably, we found that the ATF3 gene, which is involved in the complex process of cellular stress response, has expression changes in tuberculosis, influenza, AECOPD and CAP." (PMID 36059536, 2022). "In mice, after influenza-induced lung injury, ATF3 expression increases in lung endothelial cells, but not other proliferating cell types such as lung epithelial AT2 cells." (PMID 37515150, 2023). "Although Atf3 expression has been reported in proliferating AT2 cells in mice infected with Streptococcus pneumoniae, we did not observe an increase in Atf3-positive AT2 cells or in Atf3-positive mesenchymal cells following influenza infection." (PMID 37233732, 2023). "However, XAF1 and ATF3 have no reported roles in response to influenza infection and thus represent valuable predictions for further investigation." (PMID 22074594, 2011).
keloid (4 papers, 2021 to 2024). An irregularly shaped, elevated mark on the skin caused by deposits of excessive amounts of collagen during wound healing. "Consistently, western blot analysis showed that up-regulation of ATF3 significantly promoted levels of MMP1/2/9/13, whereas siRNA ATF3 led to an inhibition of MMP1/2/9/13 in keloid fibroblast cells." (PMID 33315500, 2021). "As a result, MTT assay showed that ATF3 up-regulation significantly promoted cell viability compared to the control group, whereas transfection with siRNA targeting ATF3 led to an inhibition of cell viability in keloid fibroblast cells." (PMID 33315500, 2021). "To examine the functional relevance of ATF3 in keloid fibroblasts, we evaluated the effect of overexpressing or downregulating ATF3 in fibroblast cells." (PMID 33315500, 2021). "ATF3 expression was significantly elevated in keloid tissues when compared with that of normal skins and parakeloidal skin tissues." (PMID 33315500, 2021). "This study aimed to investigate the expression and biological role of ATF3 in the pathogenesis of keloids." (PMID 33315500, 2021). "In the present study, we detected the expression pattern of ATF3 in normal skins and keloid tissues, and evaluated its functional roles in keloid fibroblast behaviors." (PMID 33315500, 2021). "ATF3 expression in normal skins and keloids was evaluated by real-time PCR, western blot and immunohistochemistry." (PMID 33315500, 2021). "The present study provides new insights into the role of ATF3 in human keloid tissues." (PMID 33315500, 2021). "Additionally, immunohistochemical analysis showed that the protein expression level of ATF3 was obviously up-regulated in keloid tissues." (PMID 33315500, 2021). "ATF3 promoted cell invasion and reduced apoptosis in keloid fibroblasts." (PMID 33315500, 2021). "To prove such a hypothesis, we detected the expression profile of ATF3 in human keloid tissues and evaluated its effects on keloid fibroblast cell growth, apoptosis, invasion and collagen production." (PMID 33315500, 2021). "In the present study, we hypothesized that ATF3 is involved in the pathogenesis of keloids by activating TGF-β/Smad signaling." (PMID 33315500, 2021). "Data showed that ATF3 was dramatically up-regulated in keloid tissues." (PMID 33315500, 2021). "Collectively, these data suggest that ATF3 could elevate the expression of MMPs and promote the invasion of keloid fibroblast cells." (PMID 33315500, 2021). "In the present study, we found that mRNA and protein expression of ATF3 was significantly elevated in keloid tissues as compared with that of normal healthy controls and parakeloidal skin tissues, suggesting that ATF3 may be involved in the pathogenesis of keloid tissues." (PMID 33315500, 2021). "In addition, downregulation of ATF3 could suppress cell growth and invasion, promoted cell apoptosis, and inhibit collagen synthesis in keloid fibroblasts, suggesting that ATF3 serves as a novel target for the management of keloids." (PMID 33315500, 2021). "However, it remains unknown whether ATF3 could regulate the cellular behaviors of keloid fibroblasts." (PMID 33315500, 2021). "Moreover, it is reported that ATF3 could also regulate cell growth, apoptosis, invasion, and collagen synthesis in keloid fibroblast through TGF-beta/SMAD signaling pathway." (PMID 34966780, 2021). "In detail, it has previously been found that ATF3 induces proliferation and invasion and inhibits apoptosis via TGFβ1/SMAD2/3 signalling in keloid fibroblasts." (PMID 38256034, 2024). "However, the expression pattern and biological role of ATF3 in keloid fibroblasts remain unknown." (PMID 33315500, 2021). "Moreover, ATF3 could reduce the apoptosis rate of keloid fibroblast cells." (PMID 33315500, 2021). "Conversely, transfection with siRNA targeting ATF3 led to decreased cell viability and collagen synthesis via inhibiting TGF-β1 and FGF2/8 production in keloid fibroblasts." (PMID 33315500, 2021).
keloid (continued). "Additionally, the functional relevance of ATF3 and TGF-β/Smad pathway in activated keloid fibroblasts was investigated." (PMID 33315500, 2021). "Collectively, ATF3 could promote growth and invasion, and inhibit apoptosis via TGF-β/Smad pathway in keloid fibroblast cells, suggesting that ATF3 might be considered as a novel therapeutic target for the management of keloid." (PMID 33315500, 2021). "Conversely, transfection with siRNA targeting ATF3 led to decreased cell viability and collagen synthesis via inhibiting transforming growth factor-β1 (TGF-β1) and fibroblast growth factor 2/8 (FGF2/8) production in keloid fibroblasts." (PMID 33315500, 2021). "Our data showed that ATF3 potently promotes growth and invasion, and suppresses apoptosis in keloid fibroblasts via activating TGF-β/Smad pathway, suggesting that ATF3 might serve as a novel therapeutic target for the management of keloid." (PMID 33315500, 2021).
liver disease (4 papers, 2020 to 2025). "This study showed that rs225014 (DIO2), rs532446 (GADD45A), rs12031994 (AKT3), rs11119982 (ATF3), rs10865710 (PPARG) are associated with the increased risk of liver disease progression in chronic hepatitis b carriers." (PMID 37059745, 2023). "As a result, our study demonstrated that rs225014 (DIO2), rs532446 (GADD45A), rs12031994 (AKT3), rs11119982 (ATF3), rs10865710 (PPARG) might contribute to the increased risk of liver disease progression in chronic hepatitis b carriers." (PMID 37059745, 2023). "Reports concerning the expression and function of ATF3 in liver diseases remain scarce so far." (PMID 33311456, 2020).
lymph node metastasis (4 papers, 2013 to 2021). "Additionally, ATF3 expression was negatively associated with the clinical stage (P = 0.041), lymph node metastasis (P = P-0.039), poor OS (P = 0.056), and DFS (P = 0.021)." (PMID 33816467, 2021). "Positive expression rate of ATF3 was significantly correlated with TNM stage (P=0.038), invasion (P=0.029), lymph node metastasis (P=0.026), and number of metastatic lymph nodes (P=0.039), but not with patients’ age and primary tumor size (P>0.05)." (PMID 24494067, 2013). "Furthermore, ATF3 expression showed significant correlation with TNM stage, invasion, lymph node metastasis and number of metastatic lymph nodes (P=0.038, P=0.029, P=0.026, and P=0.039 respectively), and did not correlate with patients’ age and tumor size (P>0.05)." (PMID 24494067, 2013).
lymphoma (4 papers, 2011 to 2023). A malignant (clonal) proliferation of B- lymphocytes or T- lymphocytes which involves the lymph nodes, bone marrow and/or extranodal sites. "The peripheral neuropathy was also validated by ATF3 expression in lymphoma-innervating cervical DRGs in the late phase (days 40–60) but not in the early phase (day 20)." (PMID 36520531, 2023). "Immunohistochemical analysis of lymph nodes of ATL patients showed that lymphoma cells indeed expressed ATF3." (PMID 21414204, 2011).
nasopharyngeal carcinoma (4 papers, 2021 to 2024). A carcinoma arising from the nasopharyngeal epithelium. "MRVI1-AS1 inhibits miR-513a-5p miR-27b-3p to upregulate activating transcription factor 3 (ATF3), then increasing nasopharyngeal cancer’s sensitivity to paclitaxel by modulating the Hippo-TAZ signaling pathway." (PMID 36973749, 2023). "rs41545520G creates a binding site for the transcriptional repressor, ATF3, leading to reduced HLA expression in nasopharyngeal carcinomas and consequently resulting in reduced presentation of tumour-associated antigens to CD8+ T lymphocytes and increased immune evasion." (PMID 39355248, 2024). "Similarly, ATF3 promotes nasopharyngeal cancer cell sensitivity to paclitaxel." (PMID 34098867, 2021).
osteoporosis (4 papers, 2016 to 2025). A condition of reduced bone mass, with decreased cortical thickness and a decrease in the number and size of the trabeculae of cancellous bone (but normal chemical composition), resulting in increased fracture incidence. "We then investigated the possibility of the involvement of ATF3 expressed by osteoclast precursors in pathogenesis in an osteoporosis mouse model using GST-RANKL fusion protein injections." (PMID 27480204, 2016). "To analyze the effects of ATF3 on osteoporosis, we assessed the bone formation markers." (PMID 36340581, 2022).
periodontitis (4 papers, 2024 to 2025). An acute or chronic inflammatory process that affects the tissues that surround and support the teeth. "Among these upregulated genes during periodontitis, Egr1, Atf3, and Zfp36 code for transcription factors that regulate expression of genes associated with control of inflammatory responses." (PMID 39588378, 2024). "Additionally, although ATF3 expression markedly increased in chronic periodontitis patients, it is difficult to draw definitive conclusions due to the limited sample size of only one case (right; accession number GSE7321)." (PMID 40430099, 2025). "Targeting ATF3 may represent a novel therapeutic strategy for managing age-related oral diseases, such as chronic periodontitis." (PMID 40430099, 2025). "Comparing the Average global expression profile of neutrophils from healthy PDL versus neutrophils from PDL with periodontitis revealed increased expression of genes such as Il1b, Il1rn, Cebpb, Colec12, Ptgs2, Zfp36, Egr1, Atf3, Csf1, and Lars2 in periodontitis." (PMID 39588378, 2024). "The results indicated that, although not statistically significant, ATF3 was expressed at higher levels in patients with periodontitis compared to healthy individuals (left; accession number GSE27993)." (PMID 40430099, 2025). "Importantly, ATF3, FOS, and JUN, that function in Tumor Microenvironment and PI3K Signaling in B Lymphocytes pathways, were exclusively downregulated in periodontitis in the non-diabetic patients." (PMID 38241313, 2024).
preeclampsia (4 papers, 2014 to 2025). Preeclampsia is a hypertensive disorder of pregnancy that is characterized by new-onset hypertension with proteinuria presenting after 20 weeks of gestation, and depending on mild or severe forms may initially present with severe headache, visual disturbances, and hyperreflexia. "We also conducted an analysis of ENCODE Chip Seq data to infer common transcription regulatory networks of selected genes (such as TTD genes and GTF2E1) and gene regulators (such as EGFR, ATF3, and FLT1) implicated in preeclampsia." (PMID 24885447, 2014). "ATF3 and EGFR were implicated as the main regulators of preeclampsia development in our previous integrative transcriptome analysis." (PMID 24885447, 2014). "In particular, the expression of ATF3 is significantly decreased in preterm placentas, and ATF3 is the regulator of soluble fms-like tyrosine kinase 1 (sFlt-1) and soluble Endoglin (sEng), which are important markers of premature delivery and preeclampsia." (PMID 40233080, 2025). "ATF3 has been shown to cross-talk to NF-κB and to act as a negative regulator of pro-inflammatory responses in different settings, such as preeclampsia, inflammation after cerebral injury, and Toll-like receptor 4 signaling, in the latter case by direct binding to the p65/RelA subunit of NF-κB." (PMID 35115943, 2021). "Our subsequent integrative transcriptome analysis shed further light on the link between impairment of TFIIH-mediated functions in placenta and induction of molecular mediators of clinical symptoms of preeclampsia through dysregulation of EGFR- and ATF3-dependent pathways." (PMID 24885447, 2014).